IDO1 (indoleamine 2,3-dioxygenase 1)
Diseases named in the same sentence as IDO1 in open-access papers (continued):
Sharing a sentence is not in itself a finding about the gene and the disease.
atherosclerosis (continued). "In atherosclerotic blood samples or foam cells, we confirmed that the expression and activity of IDO1 could accelerate the developmental process of atherosclerosis." (PMID 31637003, 2019). "These experiments indicate that IDO1 could be protective against atherosclerosis possibly by an immune-inflammatory response." (PMID 31186442, 2019). "IDO1 also had proatherosclerotic functions in the developmental stages of atherosclerosis." (PMID 31637003, 2019). "While expression of IDO1 by pDCs seems counterintuitive, IDO1-expressing SigH+ pDCs have been shown to play an immunoprotective role in animal models of multiple sclerosis and atherosclerosis." (PMID 31555267, 2019). "The in vivo study using ApoE−/− mice showed that treatment with the IDO1 inhibitor 1-MT could significantly reverse the enhanced IDO1 activity and attenuate atherosclerosis progression in the early stage of atherosclerosis." (PMID 31637003, 2019). "Before oxLDL treatment (before foam cell formation, before atherosclerosis was established), IFN-γ-induced IDO1 exhibited greater promotion on the degree of foaming than that after oxLDL treatment (after foam cell formation, after atherosclerosis was established)." (PMID 31637003, 2019). "They underscore the intricate and interconnected relationship between IDO1-mediated tryptophan metabolism and subsequent pathophysiological events in the context of atherosclerosis.In addition to its protective role, IDO1 also plays a promotive role in the development of atherosclerosis." (PMID 38883986, 2024). "Therefore, the administration of IDO1 inhibitors may prove to be an effective preventive and therapeutic strategy for the early stages of atherosclerosis." (PMID 39120289, 2024). "Therefore, IDO1 seemed to show greater promoting effects on the degree of foaming, cell apoptosis and inflammatory factor production in the developmental process of atherosclerosis than in established atherosclerosis." (PMID 31637003, 2019). "Modulation of IDO1 could be a good method for alleviating atherosclerosis." (PMID 31637003, 2019). "Therefore, inhibition of activated IDO1 could be a treatment for atherosclerosis, and IDO1 inhibitors have good prospects in the prevention of atherosclerosis." (PMID 31637003, 2019). "In conclusion, before and after oxLDL treatment, IFN-γ-induced IDO1 exhibited different degrees of promotion on foaming, suggesting that the effect of IDO1 on foaming in the developmental process of atherosclerosis was greater than that in established atherosclerosis." (PMID 31637003, 2019). "Our data indicated that 7.0 weeks of HFCD feeding represents a suitable time point to study both atherosclerosis and NASH as concomitant diseases, and this protocol was selected to evaluate the role of IDO1 in disease." (PMID 35563591, 2022). "Using blood samples of atherosclerotic patients, the expression and activity of IDO1 and TDO were found to vary with the grade of the histological classification of atherosclerosis patients." (PMID 31637003, 2019). "Here, using human aorta samples, the codistribution of IDO1/TDO and lymphocytes/macrophages was demonstrated in human atherosclerotic plaques for the first time, indicating the involvement of IDO1 and TDO in the immune responses in atherosclerosis." (PMID 31637003, 2019). "Here, the expression patterns and activities of IDO1 and its isoenzyme tryptophan 2,3-dioxygenase (TDO) in aortas and blood samples of patients with atherosclerosis were investigated." (PMID 31637003, 2019). "The finding of the localization of IDO1 and TDO with CD3-positive T cells suggested the involvement of IDO1 and TDO in this T cell-mediated immune response in atherosclerosis." (PMID 31637003, 2019). "In this study, we investigated the expression patterns and activities of IDO1 and TDO in aortas and blood samples of patients with atherosclerosis." (PMID 31637003, 2019).
atherosclerosis (continued). "Compared to that of the early atherosclerosis stage, the expression and activity of IDO1 and TDO were downregulated in the advanced atherosclerosis stage." (PMID 31637003, 2019). "We concluded that before and after atherosclerosis was established, IFN-γ-induced IDO1 exhibited different degrees of promoting effects on the degree of foaming." (PMID 31637003, 2019). "IDO1 and TDO were downregulated in the advanced atherosclerosis stage compared with that in the early atherosclerosis stage." (PMID 31637003, 2019). "Despites the fact that IDO-1 expression was largely thought to be protective, several recent studies suggest a detrimental role of IDO-1 expression in obesity, atherosclerosis, vascular inflammation, and aneurysm." (PMID 30619249, 2018). "Given the atheroprotective role of IDO1 in established atherosclerosis, the comparable downregulation of IDO1 and TDO in advanced atherosclerosis may lead to post myocardial infarction." (PMID 31637003, 2019). "In summary, IDO1 exhibited greater promoting effects on THP-M apoptosis and inflammatory factor production in the developmental process of atherosclerosis than in established atherosclerosis." (PMID 31637003, 2019). "In conclusion, our data revealed the relationship between IDO1/TDO and atherosclerotic pathological grading and indicated that IDO1 and its isoenzyme TDO were important modulators of the immunoinflammatory responses in atherosclerosis." (PMID 31637003, 2019). "The exact role of IDO1, an immunosuppressive enzyme, in the developmental process of atherosclerosis has not been fully studied, nor has that of IDO1′s isozyme TDO." (PMID 31637003, 2019). "The role of IDO1 in the process of atherosclerosis is complex and not fully understood." (PMID 39120289, 2024). "In the murine systems, the absence of IDO1 shown to protect against atherosclerosis." (PMID 34630411, 2021). "Thus, the activity of IDO1 and TDO increased in early atherosclerosis (grade I–II); however, the increase did not continue in advanced atherosclerosis (grade III)." (PMID 31637003, 2019). "The expression and activity of IDO1 and TDO increased with the grade of the histological classification in early atherosclerosis (grade I, II), but the increase did not continue in advanced atherosclerosis (grade III)." (PMID 31637003, 2019). "From the result, we found that, generally, the expression and activity of IDO1 and TDO tended to increase with the grade of the histological classification in early atherosclerosis (grade I, II), but the increase did not continue in advanced atherosclerosis (grade III)." (PMID 31637003, 2019).
pancreatic cancer (42 papers, 2014 to 2025). "A schematic overview of IDO1‐induced tryptophan deficiency results in GLUT1‐dependent upregulation of glycolysis in pancreatic cancer." (PMID 38706741, 2024). "In contrast, for pancreatic cancer it was measured indirectly; but both studies demonstrated that a lower level of IDO-1 associated with better disease outcomes." (PMID 37181043, 2023). "For example, carbidopa, an AhR agonist, suppresses IDO1 expression in pancreatic cancer cells, attenuating tumor growth." (PMID 41332472, 2025). "IDO1 overexpression is a significant immunomodulatory factor in pancreatic cancer, representing a primary therapeutic target." (PMID 41332472, 2025). "Carbidopa, an FDA-approved drug for Parkinson’s disease, acts as an AHR agonist, impeding the growth of pancreatic cancer cells by inhibiting IDO1 (indoleamine 2,3-dioxygenase-1)." (PMID 38612627, 2024). "Nitric oxide activates the IDO1/ kynuridine /AhR signaling axis, promoting pancreatic cancer progression." (PMID 38462620, 2024). "IDO1/TDO dual inhibitor RY103 blocks the kynurenine pathway in pancreatic cancer, inhibiting cell motility and demonstrating growth inhibition in vivo." (PMID 38462620, 2024). "The results showed that IDO1 expression levels in pancreatic cancers were related to CD4+ memory T cells (r, 0.61), M1-like macrophages (r, 0.46), and CD8+ T cells (r, 0.19) but not other immunosuppressive cells, consistent with our immunostaining results." (PMID 36517670, 2023). "To find the global correlations between immune infiltrates and IDO-1 expression in pancreatic cancers, we analyzed 182 PDACs (TCGA) using CIBERSORT methods." (PMID 36517670, 2023). "Carbidopa, another antiparkinsonian medication, has also been shown to be effective against pancreatic cancer by the inhibition of indoleamine-2,3-dioxygenase-1 and the potentiation of aryl hydrocarbon receptor signaling." (PMID 37847564, 2023). "Another emerging inflammatory biomarker identified in studies of both breast and pancreatic cancer was IDO-1, again related to tryptophan metabolism." (PMID 37181043, 2023). "Recent studies have shown that IDO1 expression strongly affects purine metabolism in OC and pancreatic cancer." (PMID 37240946, 2023). "Lower level of IDO-1 links the marker to possible detection of reduced disease progression in pancreatic cancer patients." (PMID 37181043, 2023). "Here we explored the potential of the FDA-approved drug carbidopa in pancreatic cancer therapy as a blocker of IDO1 expression and function." (PMID 35997090, 2022). "While this study has focused on pancreatic cancer, human IDO1 expression data suggest that our findings are relevant across a range of other human cancers, particularly colon, breast, cervix, and lung." (PMID 33831358, 2021). "Analysis of human pancreatic cancer survival data shows that high IDO1 expression correlates with worse survival." (PMID 33831358, 2021). "Analysis of public data shows that several tumor types, including pancreatic cancer, have high-IDO1-expressing subsets, and we show that IDO1 is expressed in genetically engineered mouse models for PDAC." (PMID 33831358, 2021). "Surprisingly, we also observed that IDO-1+ macrophages in metastatic lymph nodes and tumors possess multiple processes and larger body sizes in pancreatic cancer patients (unpublished data)." (PMID 34735466, 2021). "To perform metabolic analyses on cells expressing physiologically relevant levels of IDO1, we sought to evaluate the expression of IDO1/Ido1 in pancreatic cancer cells across a range of in vitro and in vivo contexts." (PMID 33831358, 2021). "Using in vitro and in vivo pancreatic cancer models, we show that IDO1 expression is highly context dependent, influenced by attachment-independent growth and the canonical activator IFNγ." (PMID 33831358, 2021).
pancreatic cancer (continued). "In this study, we focused on IDO-1 and -2, which are described to be overexpressed in some pancreatic cancer cells, and their influence on Vγ9Vδ2 γδ T cell cytotoxicity against PDAC cells and their consequences for their application in immunotherapy." (PMID 32384638, 2020). "Furthermore, IDO1 inhibition has been shown to alleviate depressive symptoms in patients with pancreatic cancer." (PMID 41332472, 2025). "Hydroxyamidine inhibitors show efficacy in CRC and pancreatic cancer by targeting IDO1." (PMID 38462620, 2024). "We aim to clarify the potential role of IDO1 in aerobic glycolysis in pancreatic cancer (PC)." (PMID 38706741, 2024). "Use of a dual inhibitor IDO1/TDO (RY103) effectively suppressed IDO1 in a pre-clinical murine pancreatic cancer model and might be a new avenue to be considered in circumventing the inhibitory action of IDO1 in NK cell-mediated cytotoxicity." (PMID 39294470, 2024). "In addition, tryptophan metabolism induced by IDO1 enzyme in pancreatic cancer cell is the source of one-carbon units for pancreatic stellate cells, which accelerates the development of PAAD." (PMID 37540295, 2023). "Next, we assessed the expression of IDO1 in a panel of human pancreatic cancer cells." (PMID 33831358, 2021). "Also, studies have shown that IDO1 is highly expressed in tumours such as cervical, stomach, colon and pancreatic cancer." (PMID 32568737, 2020). "Thus, the researchers found that a decreased kynurenine/tryptophan ratio, which suggests downregulated IDO levels, and their subsequent observation of lower levels of IDO, including IDO-1, links the marker to possible detection of reduced disease progression in pancreatic cancer patients." (PMID 37181043, 2023). "However, pancreatic tumor tissue had multiple high or very high IDO1-expressing tumors." (PMID 33831358, 2021). "Carbidopa, an AhR agonist, inhibits IDO1 expression in PDAC cells, regulating the JAK/STAT pathway to impede pancreatic cancer progression." (PMID 38462620, 2024). "Currently, there is a dual IDO1/TDO inhibitor (RY103), which has been demonstrated to be effective in suppressing IDO1 in a pre-clinical murine pancreatic cancer model." (PMID 35327550, 2022). "Regarding immune inhibitors, IDO-1 regulates the immune response via NF-κB; CD276 can help promote pancreatic carcinoma metastasis and infiltration by activating the TLR4–NF-κB signaling pathway, via upregulated expression of IL-8 and VEGF." (PMID 34367975, 2021). "NLG919 inhibits the expression of IDO-1, which converts tryptophan (Trp) into kynurenine (Kyn), thus modulating the immunosuppressive TME in pancreatic cancer by increasing the proportion of DCs and T cells while reducing the proportion of regulatory T cells (Tregs)." (PMID 40538751, 2025). "The RNA‐binding protein BICC1 enhances chemoresistance in pancreatic cancer by upregulating IDO1 expression, suggesting that targeting the BICC1/IDO1/Trp metabolic axis could help overcome drug resistance." (PMID 41332472, 2025). "In light of the potential role of IDO1 as a driver of hostile TME in PDAC and NAD+ as a key coenzyme in anti-tumor immune response, this review urges focus on extensive research and initiation of clinical trials using IDO1 and NAMPT inhibitors in pancreatic cancer in the future." (PMID 37456260, 2023). "However, the failure of IDO-1 inhibitors in clinical trials did not support the dominant immunosuppressive effects of IDO-1 in solid tumors, especially in pancreatic cancers." (PMID 36517670, 2023).
Obesity (40 papers, 2016 to 2025). Accumulation of substantial excess body fat. "This is a result of the over-expression of IDO1 and vitamin B6 deficiency, which exacerbate obesity and insulin resistance." (PMID 37895892, 2023). "Seven of the genes were downregulated by obesity and reversed by VSG specific weight loss including Ido1, Aldoc, Tmem125, Dgki, Slc7a4, Msc, and Ephb3, while four were inversely regulated with obesity elevating Klhl5, Nek6, Arhgap20, and Hp." (PMID 35775614, 2022). "IDO1 upregulation is a hallmark of obesity, and its deletion or inhibition improves insulin sensitivity, preserves the gut mucosal barrier, decreases chronic inflammation, and regulates lipid metabolism in liver and adipose tissues." (PMID 34473644, 2021). "Experimental obesity was associated with high IDO1 expression and Kyn levels in the stromal vascular fraction of visceral white adipose tissue (SVF WAT)." (PMID 34394118, 2021). "Tryptophan breakdown via indoleamine 2,3-dioxygenase-1 (IDO-1) along the kynurenine axis concomitant with a pro-inflammatory state was found to be more active in BD, and associated with overweight/obesity." (PMID 34829665, 2021). "Additionally, the IDO-1 activity was shown to be increased in overweight and obesity, and was presumably indirectly driven via linked proinflammatory cascades." (PMID 35566641, 2022). "Specifically, individuals with obesity have a significantly higher concentration of Kyn and IDO1 in adipose tissue, which is associated with an imbalance in Th17/Treg cells; suggesting a mechanistic link between altered tryptophan metabolism, obesity and CRC pathogenesis." (PMID 33916690, 2021). "Interestingly, patients with stage 2, stage 3 and the most severe stage 4 BC are characterized by a high expression of IDO1 as well as patients with extreme weight (BMI 24.9–29.9) and obesity (BMI 30–34.9), which have been associated with less favorable outcome in BC patients." (PMID 40287406, 2025). "In obesity and metabolic disorders, dysfunctional adipocytes upregulate IDO1, thereby becoming an additional peripheral source of KYN." (PMID 41516008, 2025). "A recent article demonstrates that in western diet‐induced metabolic syndrome, IDO1 inhibition positively regulated lipid metabolism, indicating the potential of IDO1 inhibitors in regulating metabolic disorders, such as obesity." (PMID 38706741, 2024). "IDO1 is upregulated during tryptophan excess (diet/obesity) and in aging individuals and generates kynurenine from tryptophan, while depleting the tryptophan‐based metabolism of serotonin and indoles." (PMID 36935524, 2023). "The role of IDO1 and AHR in developing obesity was further indicated by the facts that IDO1 and AHR knockout mice showed a significant decrease in body weight compared to WT control mice." (PMID 35154484, 2022). "The discrepancy of plasma Kyn between HFD-fed KO mice and NCD-fed WT mice indicates that IDO1 in adipocytes not only mediates altered Kyn production in subjects with obesity, but also involves in the maintenance of Kyn homeostasis in healthy individuals." (PMID 35715443, 2022). "In regard to systemic inflammation, obesity is a proinflammatory state and the IDO-1 enzyme is known to be activated by inflammation." (PMID 35757166, 2022). "Collectively, the overexpressed IDO1 along with the decreased PLP synergistically leads to an elevation of Kyn in WAT during obesity, subsequently boosting the plasma Kyn." (PMID 35715443, 2022). "In contrast to these studies, we observed a dramatic increase of Kyn and IDO1 in subjects with obesity." (PMID 35715443, 2022). "Since Kyn is a Trp downstream metabolite catalyzed by IDO127, Ido1−/− mice were next employed to dissect the exact role of Kyn in obesity." (PMID 35715443, 2022).